HIF1A (hypoxia inducible factor 1 subunit alpha)
Diseases named in the same sentence as HIF1A in open-access papers (continued):
Sharing a sentence is not in itself a finding about the gene and the disease.
tumor (continued). "In summary, the present study confirmed that SFN not only affects ECs function but also the interaction between HCC cells and ECs by inhibiting STAT3/ HIF-1α /VEGF signalling in the cancer cells, which results in the suppression of angiogenesis induced by HCC cells leading to an anti-tumor effect." (PMID 28978924, 2017). "Importantly, we detected intense widespread nuclear HIF1α and cytoplasmic OATP expression in tumor samples, which indicates that these two molecules are involved in the preferential uptake of NIRF dyes." (PMID 28635650, 2017). "The actions of MyD88 in regulating the expression of these factors is likely to involve both direct and indirect mechanisms, mainly coordinating the interplay between NF-κB, HIF1α, and STAT3 transcription factors, which are well known for its roles in tumor development and inflammation." (PMID 28662055, 2017). "Furthermore, the engagement of the HIF-1α/VEGF axis by estrogen- and endothelin-activated GPER signaling has been shown to stimulate angiogenesis and tumor growth both in vitro and in vivo, as evidenced in breast and hepatic cancer models as well as in CAFs." (PMID 29240722, 2017). "Given the importance of the hypoxic tumour microenvironment for TAMs and tumour-infiltrating myeloid cells, it is not surprising that PD-L1 was identified as a direct HIF-1α target gene in myeloid-derived suppressor cells (MDSCs)." (PMID 28536364, 2017). "We identified HIF-1α is a direct target of miR-1, and most important, Smad3 regulated and interacted with HIF-1α, leading to increasing Smad3 activity, which implies the contribution of a feed forward loop in regulation of tumor glycolysis and proliferation." (PMID 28471448, 2017). "The present study demonstrated that ADM promoted tumor angiogenesis through upregulating HIF-1α/VEGF in EOC in vitro, ADM/HIF-1α/VEGF might be a new signaling pathway playing a role in this process." (PMID 28091613, 2017). "We evaluated the combination effect of BA/CDM on tumor suppression through an in vivo xenograft tumor development study using THP1 cells, and we also investigated the potential role of SOD2 and HIF1α through lentivirus-carrying SOD2/HIF1C overexpression in THP1 cells." (PMID 29212263, 2017). "Moreover, deletion of Tgfbr1 and Pten in murine epithelia activated HIF-1α, CD73 and subsequently induced A2AR overexpression in tumor infiltrating immune cells, accumulating immunosuppressive CD4+ Foxp3+ Tregs in the stroma of tumors." (PMID 28592285, 2017). "Therefore, we proposed that HIF‐1α would bind to HRE in the promoters of AEG‐1 after hypoxia treatment and enhance AEG‐1 promoter activity to induce tumor growth and migration." (PMID 28401704, 2017). "Among the 151 tumours, 49 tumours were positive for both GATA3 and HIF-1α staining." (PMID 28263977, 2017). "In a wide range of different tumor types, HICR was shown to be reversed by HIF-1α inhibition." (PMID 29036915, 2017). "Under aerobic conditions, proline residues (Pro402 and Pro564) located in the oxygen-dependent degradation domain of HIF-1α are hydroxylated by PHD2, which results in recognition of the subunit by the VHL protein (von Hippel-Lindau tumour suppressor), a part of the ubiquitin ligase complex E3." (PMID 27326424, 2017). "Here we show that tumor-take and tumor growth of xenografted SCLC cells in mice are not drastically impaired by knocking down HIF1A by shRNA." (PMID 28430666, 2017). "A similar analysis for MCT1, MCT4 or LAc+ did not demonstrate a significant correlation to survival (data not shown), suggesting that HIF-1α/CAIX affects tumor aggressiveness beyond their co-expression with MCT1 or MCT4." (PMID 28099149, 2017). "The excised tumor tissue was assessed for changes in MDR-1 and TFPI1 protein abundance in response to metformin exposure (we previously found TFPI1 involved in MDR development), as well as HIF1α protein abundance." (PMID 29211738, 2017).
tumor (continued). "Besides mTOR, HIF-1α plays a crucial role by upregulating its targets expression, BNIP3 and BNIP3L, to activate autophagy in tumor cells." (PMID 28729825, 2017). "Finally, given the fact that HIF-1α has been shown to regulate many important cancer metabolic processes, HIF-1α has been an attractive target for developing anti-tumor therapy." (PMID 28883660, 2017). "IL-8 has been reported to be down-regulated by HIF-1α, while up-regulation of NRF2 could reverse the blocking effect of HIF-1α on IL-8, suggesting that NRF2 may be involved in tumor angiogenesis through the IL-8 pathway." (PMID 29268703, 2017). "Furthermore, to our surprise, we found that at least in certain cancer cell lines / tumor entities, elevated STK33 expression can further boost the hypoxia-triggered HIF-1α activation and subsequent vascularization." (PMID 29100402, 2017). "Although GLUT-1 AS-ODNs and HIF-1α AS-ODNs did not influence the weight or volume of the xenografts, they did increase tumor AI, increase tumor necrosis and decrease tumor MVD." (PMID 28410229, 2017). "Immunohistochemistric analysis revealed that the percentages of EGFR+ or KI67+ cells and the levels of HIF-1α expression and microvessel density (MVD) in the XWLC-05-miR-370 tumor sections were significantly lower than that in the XWLC-05-miR-NC tumor sections." (PMID 29152147, 2017). "Moreover, we found that, in clinical samples of HNSCC, the expression and distribution of GATA3 and HIF-1α are significantly correlated, implying that GATA3 can interact with HIF-1α in tumour cells to regulate their behaviours in vivo." (PMID 28263977, 2017). "Additionally, data was shown that TAp73−/− mice show high tumor incidence and that TAp73 opposes HIF-1 activity by interacting directly with HIF-1a." (PMID 28300843, 2017). "As expected, the increased protein expression of HIF-1α, VEGF, pVEGFR2, and CD31 (PECAM-1), a specific endothelial cell marker, in tumor tissues determined by immunohistochemical staining or Western blotting assay was also greatly suppressed after AE-AS treatment." (PMID 28710377, 2017). "HIF1α tumour fractions did not correlate with any of the central tendency parameters, but did show significant positive correlation with SD of R2* pre and post O2 and skewness of R1 pre O2 (P < 0.048)." (PMID 28550313, 2017). "However, HIF-1α and HIF-2α positivity was found to be related to a poor prognosis and low survival rates in many tumor types and ccRCCs in the literature, as in the present study." (PMID 27583351, 2017). "HIF-1α preferentially drives the transcription of genes that control glycolysis, angiogenesis and glucose transport pathways, while HIF-2α is involved in the regulation of genes important for tumor growth and cell cycle progression." (PMID 29084538, 2017). "Thus, while hypoxia before the angiogenic switch slows proliferation rates, the overexpression of HIF1α and VEGF and the increase in migration leads to overall increases in tumor growth." (PMID 28693495, 2017). "Additionally, HIF-1α and LOX are highly expressed in OC tissues and significantly correlate with tumor grade and lymph node metastasis." (PMID 28725636, 2017). "With regard to HIF-1α and CAIX, in agreement with previous reports, an almost complete overlap of the two hypoxic biomarkers was detected, as shown by immunostaing of serial tumor slices." (PMID 28099149, 2017). "It seems that AHR activation in AML cells plays an inhibition effect on AML tumor growth; this is consistent with the recent finding that AHR may promote HIF1α degradation in lymphocyte metabolism and indirectly suppress the HIF1α pathway." (PMID 29212263, 2017). "Western blot analyses showed that Ang II increased HIF-1α protein levels of CNE2 cells in a dose-dependent manner under normoxic conditions, indicating that Ang II can stimulate HIF-1α accumulation in tumor cells in vitro." (PMID 28205588, 2017). "EZN-2968 reduces HIF-1α expression as well as VEGF secretion, and attenuates tumor growth." (PMID 29295482, 2017).
tumor (continued). "Positive HIF-1a staining was observed in the tumor cells after TACE, and its localization was similar to MTA1, which clustered at the periphery of substantial central necrosis and scattered at the areas near focal necrosis of tumor peripheral zone." (PMID 28589145, 2017). "Interestingly, the metabolic shift was reversed by silencing of HIF-1α, suggesting that AMPK and HIF-1α have opposing roles in the control of tumor metabolism." (PMID 28443281, 2017). "However, as HIF1α is known to interact with CTLA-4 and its receptors, HIF-mediated blockade of CTLA-4 was shown to reduce the frequency of Tregs in the tumor." (PMID 28447025, 2017). "In recent studies, the inhibition of HIF-1α expression failed to block angiogenesis induced by the tumor, allowing the tumor to survive and proliferate." (PMID 28053598, 2017). "Of interest, HIF-1α gene expression was unchanged (HIF is rather expected to change on protein than on mRNA level), while hypoxia-responsive CA9 was highly increased in tumor samples, emphasizing the relevance of hypoxia-responsive factors in our CRC patient cohort." (PMID 27589845, 2016). "cDDP-induced HIF-1α expression resulting in sensization to ADI-PEG20 treatment supports the current ongoing clinical trials using cDDP and ADI-PEG20 in treating multiple tumor types (NCT0166518)." (PMID 27765932, 2016). "Moreover, phosphorylation of HIF-1α at S668 lead to an expression of HIF-1 target genes and promoted tumor angiogenesis, proliferation, and tumor growth." (PMID 26942179, 2016). "Apart from VEGF, HIF-1α, and TGF-α, angiopoietin-2 (Ang-2), a ligand of the Tie2 tyrosine kinase receptor, has also been reported to be involved in TAM-regulated angiogenesis in tumor microenvironment." (PMID 27191744, 2016). "Our work presents an example of one mechanism, outside of the sustained effects imparted by hypermethylation, whereby expression of the mutant IDH1 can compromise HIF1α induction in response to hypoxia to modify the ECM and alter tissue mechanics and tumour aggression." (PMID 27820599, 2016). "The same effect has been attributed to the mechanisms of tumor neoangiogenesis: Tumor cells stimulate endothelial cell migration, tube formation, and tumor angiogenesis through the induction of HIF-1 in endothelial cells due to HIF-1α stabilizing activity of released lactate." (PMID 27990124, 2016). "In the absence of oxygen, HIF1α ensures (tumor) cell survival by coordinating the broad metabolic reprogramming at the transcriptional level." (PMID 27166192, 2016). "An heterogeneous tissue staining of HIF-1α,HIF-2α, and EGFR has been observed in this tumor." (PMID 27303300, 2016). "However, PD98095 had no obvious effect on the growth of the SCLC tumor xenografts, and HIF-1a and CD34 expression in this tumor tissue showed only marginal changes." (PMID 27456341, 2016). "Although HIF-1α is a key factor for the regulation of angiogenesis during tumor progression, zingerone did not affect hypoxia-induced HIF-1α protein levels in tumor cells." (PMID 27323807, 2016). "In particular, the effects of arsenite on the regulation of HIF-1α under tumor-promoting conditions like hypoxia have never been explored." (PMID 27286880, 2016). "While this is inconsistent with our observations that HIF-1α knockdown attenuated RKO xenograft growth compared with control and NQO1 overexpressed tumours, histological evaluation of these tumours showed reduced proliferation and increased apoptosis in HIF-1α-deficient xenografts." (PMID 27966538, 2016). "As such, tumor areas that have undergone reoxygenation to restore oxygen conditions would stain negative for HIF-1α expression." (PMID 27882053, 2016). "We observed that HIF1α mRNA in Tumor-3 tissue was 6.7 times higher than its paired non-tumor liver tissues; in contrast, HIF1α mRNA only increased by ~1.5 folds in the tumor tissues of other two sample pairs." (PMID 27363021, 2016).
tumor (continued). "Of interest, our findings support a positive feedback mechanism in which ET-1, that is able to stabilize HIF-1α promotes the autoregulatory HIF-1α-mediated transcription of ET-1 itself that, in turn, sustains tumor cell invasion, and angiogenic effects on surrounding endothelial cells." (PMID 26909598, 2016). "But the results about the relationship between the plasma level of HIF-1α and tumor patients have not been reported yet." (PMID 26853843, 2016). "When we counted the cells in the immunofluorescent images of the tumor tissues around necrotic areas, SOX2+ HIF-1α+ RNApII-S2P-/low cells and NANOG+ HIF-1α+ RNApII-S2P-/low cells accounted for 0–6.3% and 0–4.7% of the cells in the microscopic field, respectively." (PMID 26799577, 2016). "Correspondingly, expression of pAKT has been correlated with the expression of HIF-1α in patient biopsies of different tumor types, including invasive breast carcinoma and non-small-cell lung cancer (NSCLC)." (PMID 28031935, 2016). "Importantly, HIF1A and HIF2A stabilization have different effects on promoting tumor growth: HIF1A activates glycolytic genes while HIF2A promotes growth and angiogenesis." (PMID 27128972, 2016). "The 1-, 3- and 5-year postoperative survival rate of patients with NSCLC were 91%, 69%, 59% respectively, and not correlated with the plasma level of HIF-1α, age, gender, tumor differentiation grade, diameter of tumor and smoking status (P > 0.05)." (PMID 26853843, 2016). "In tumor cells, FAC was able to counteract the effect of Dynamin-2 inhibition on HIF-1α." (PMID 27589831, 2016). "When BxPC-3 tumor cells were treated for 8 h with IFN-γ alone or in combination with PEG-catalase (to increase intracellular peroxide detoxifying capacity), the induction of HIF-1α by IFN-γ was decreased in a PEG-catalase concentration-dependent fashion." (PMID 27637085, 2016). "MR-17-5p upregulates the expression of cIAP1, HIF-1α, and TRAIL R1, which might play roles in the radioresistance of irradiated tumor cells." (PMID 27285985, 2016). "We therefore performed simultaneously IHC staining for HIF-1α and common leukocyte antibody (CD45) in a subset of tumor samples (n = 95), to exclude that the HIF-1α expressing cells in the stroma are tumor associated macrophages (TAMs) or tumor infiltrating lymphocytes (TILs)." (PMID 27634881, 2016). "Tumours derived from R132H IDH1 GBM cells expressing the V737N integrin demonstrated increased mechanosignalling, and expressed elevated levels of both HIF1α and TNC." (PMID 27820599, 2016). "TNM (P<0.0001), tumor size (P=0.001), lymph nodes metastasis (P<0.0001), CA19-9 (P=0.005), grade of differentiation (P<0.0001), HIF1A SNPs (P<0.0001), or HIF-1α expression (P<0.0001) all showed significant association with OS of patients with PDAC but age has no impact of PDAC prognosis." (PMID 26872370, 2016). "In this study, we showed that the HIF-1α was downregulated by LDHA-siRNA combined with RT, suggesting hypoxia could be suppressed by reduced LDHA, thus leading to inhibition of tumor survival genes and promoting radiosensitization." (PMID 27708237, 2016). "Within HIF1α-positive tumour areas, large numbers of tumour cells displaying cytoplasmic HMGB1 expression were observed and double-labelling experiments identified numerous cells co-expressing HMGB1 and HIF1α." (PMID 27426915, 2016). "Importantly, we showed intense widespread nuclear HIF1α and cytoplasmic OATP1B3 expression in NIRF-positive tumor samples." (PMID 27329598, 2016). "We found that the nuclear score for RPS7 was negatively correlated with HIF-1α, GLUT4 or LDHB staining in tumor tissues (p < 0.05), evidenced by the representative images showing the high expression of RPS7 corresponding to the low expressions of HIF-1α, GLUT4 or LDHB in same tissues, or vice versa." (PMID 26735579, 2016).
tumor (continued). "To confirm whether the expression of RPS7 can up-or down-regulate HIF-1α, GLUT4 and LDHB in vivo, we performed IHC analyses on tumor sections from all the experimental groups." (PMID 26735579, 2016). "To determine whether the tumor growth of HIF1α-KD-VD3/SAHA induced cells decreasedin vivo, we compared the tumorigenicity of HIF1α-KD-VD3/SAHA induced cells with LACSCs in NOD-SCID mice in xenograft experiments." (PMID 27588392, 2016). "Furthermore, in-vitro and in-vivo studies have confirmed that hypoxia-induced EMT is tightly regulated by HIF-signaling pathways, which also contribute to additional tumor invasiveness by late release of VEGF, being mediated and sustained by HIF-1α." (PMID 26760782, 2016). "Since we have shown that TR-764 reduces the levels of HIF-1α in hypoxic conditions, we wanted to verify whether the drug was able to induce an impairment in the levels of HIF-1α in the tumor samples of the animals treated with the test compound." (PMID 27292568, 2016). "Among tumor-secreted angiogenic molecules, VEGF and ET-1 are particularly involved in the reciprocal exchanges between malignant cells and endothelial cells within hypoxic microenvironment, via HIF-1α." (PMID 26909598, 2016). "Tumour conditioned medium shows the same capacity to induce VEGF and ARG1 expression in an HIF1α dependent manner, as indicated by the fact that their expression is prevented in an HIF1α null background." (PMID 27083002, 2016). "Therefore, we further investigated the affect of hyperbaric oxygen on the expression of IL‐1, TNFα, and other factors including HIF‐1α, NF‐κB, VEGF, and MMP9, which were closely related to tumor development." (PMID 27734611, 2016). "Moreover, MCU silencing downregulates HIF‐1α expression, thus impairing the transcription of HIF‐1α‐target genes involved in tumor progression." (PMID 27138568, 2016). "Surprisingly, Epas1 mRNA levels were only slightly elevated in the SAHA-treated tumours compared with controls, although there was no change in Hif1a levels, as expected." (PMID 26837714, 2016). "Tumor samples from the breasts of mice in model group, escin Ia (2 mg/kg, 4 mg/kg)-treated groups and BAPN (100 mg/kg)-treated groups were used to determine the effect of escin Ia on the expressions of HIF-1α, LOXL2 and EMT markers." (PMID 27008697, 2016). "Meanwhile, due to the structural similarity between HIF-1α and HIF-2α, HIF-2α may contribute to the production of VEGF in tumor cells as well." (PMID 27413748, 2016). "At present, our understanding of the mechanisms and consequences of HIF-1α induction in non-hypoxic tumours is limited." (PMID 26967059, 2016). "In addition to HIF-1α regulation of inflammation, HIF-2α can regulate macrophage function in tumor models, eosinophil function in the lung, and IL-6 secretion from endothelial cells (49, –, 51)." (PMID 27624128, 2016). "Moreover, increasing evidence suggests that functional contributions of HIF-1α and HIF-2α to tumour progression are context dependent." (PMID 27966538, 2016). "HIF-1α binds to the promoter region of VEGF and induces transcription and expression of VEGF, resulting in neovascularization and an increased oxygen supply in the tumor tissue." (PMID 26985249, 2016). "In EC the prognostic importance of HIF-1α protein is not established, likely due to lack of consensus in immunohistochemical evaluation of tumor protein expression." (PMID 27634881, 2016). "Immunohistochemical expression of HIF-1α and cleaved caspase 3 in stromal and tumor cells did not reveal significant difference between the RQI <5 and ≥5 groups." (PMID 27124490, 2016). "To determine the extent that HIF-1α protein accumulated in primary UM tumor cells in vivo, we performed orthotopic (intraocular) tumor cell transplantation with OCM1 cells, and observed uniform expression of HIF-1α protein in all tumor cells." (PMID 26761211, 2016).